PER2 (period circadian regulator 2)
Diseases named in the same sentence as PER2 in open-access papers (continued):
Sharing a sentence is not in itself a finding about the gene and the disease.
glioma (continued). "Initially, we investigated the TCGA and CGGA databases and discovered that Per2 and Id3 are associated with the WHO glioma grade, 5-year survival rate, and prognostic risk, and the two genes appear to be negatively correlated with each other." (PMID 35599595, 2022). "In an animal model of brain glioma, when radiotherapy was administered during the peak of Per1 or Per2 expression, the apoptosis rate of glioma cells was greater." (PMID 35877357, 2022). "Early results showed that PER2 expression was significantly lower compared to non-glioma cells, bringing out differences in the expression of clock genes between normal and malignant brain tissues." (PMID 34361055, 2021). "PER2 protein expression in gliomas has also been reported to be disturbed in comparison with normal brain tissues." (PMID 34361055, 2021). "Downregulation of the circadian genes encoding CRY2, PER1, PER2, PER3, CLOCK, REV-ERBβ, ROR-α and ROR-β was associated with significantly higher mortality rates in the glioma cohort, hinting at possible tumor suppressor roles." (PMID 32631383, 2020). "PER1 and PER2 oscillation profiles were found to vary between both glioma and normal brain tissue, albeit being within the circadian range in both." (PMID 32195174, 2020). "Previous studies have also reported that overexpression of Per2 promotes apoptosis and inhibits proliferation in glioma, breast, leukemia and lung cancer cells." (PMID 32284762, 2020). "Along the same vein, another study thought to investigate the possible epigenetic modification of PER2 gene in 92 human glioma specimens." (PMID 32195174, 2020). "Experimental evidence from our previous studies indicated that the expression of PER1 and PER2 closely correlated with the incidence and development of glioma." (PMID 31350984, 2019). "Here, we examined the role of Per2 in the response to X-ray-induced DNA damage in U343 glioma cells and in a mouse cancer model." (PMID 27036047, 2016). "Here, we examine the role of Per2 in X-ray-induced DNA damage in U343 glioma cells and an animal glioma model." (PMID 27036047, 2016). "Following low dose X-ray irradiation, we observed that lowering Per2 expression using RNAi reduces DNA damage and cell death in U343 cells and glioma tissue." (PMID 27036047, 2016). "In glioma tissue, the level of Per2 mRNA was higher in the irradiated (10 Gy) group than in the control (untreated) group at 24 hours after irradiation (p < 0.05)." (PMID 27036047, 2016). "By irradiating glioma tissue with 10 Gy X-rays, we found that DNA damage and apoptosis of glioma cells were reduced in the Per2-knockdown group compared with the other groups." (PMID 27036047, 2016). "Our findings identify Per2 as an excellent target for the clinical treatment of glioma and a reliable basis for post-radiation therapy and gene therapy for gliomas." (PMID 27036047, 2016). "In this study, we focused on how Per2 induces DNA damage and apoptosis of glioma cells after X-ray irradiation." (PMID 27036047, 2016). "We used real-time RT-PCR to measure Per1 and Per2 mRNA levels in glioma and normal tissues after treatment with ionizing radiation (15 Gy)." (PMID 25760074, 2015).
glioma (continued). "We detected apoptosis in glioma and normal tissue after irradiating animals at times when Per1 and Per2 mRNA levels were high and low." (PMID 25760074, 2015). "We observed that Per1 and Per2 mRNA levels in irradiated glioma tissue were significantly higher than in untreated glioma." (PMID 25760074, 2015). "In this research, we demonstrated that the expression of the clock oscillatory genes Per1 and Per2 shows a circadian rhythm in both glioma and normal brain tissue." (PMID 25760074, 2015). "We found differences in the circadian expression, and we observed that in glioma tissue, Per1 and Per2 expression was positively correlated with apoptosis and negatively correlated with proliferation." (PMID 25760074, 2015). "We measured the expression of Per1 and Per2 mRNA over a period of 24 h in both normal and glioma tissue from rats." (PMID 25760074, 2015). "We x-irradiated normal and glioma tissue at times when Per1 and Per2 mRNA levels were high and low in gliomas." (PMID 25760074, 2015). "We measured cell proliferation in glioma and normal tissues at ZTs when Per1 and Per2 mRNA levels were high and low, following irradiation with a single dose of x-radiation (15 Gy)." (PMID 25760074, 2015). "The expression of Per1 and Per2 in glioma tissue shows a period of approximately 12 h, but in normal tissue it shows a period of approximately 24 h." (PMID 25760074, 2015). "Future research should focus on the detailed mechanisms by which Per1 and Per2 regulate the expression of genes related to cell proliferation and apoptosis in gliomas." (PMID 25760074, 2015). "In contrast, proliferation was significantly lower and apoptosis significantly higher in glioma cells expressing high levels of Per2 (ZT0) than in cells expressing low levels (ZT8)." (PMID 25760074, 2015). "By analyzing the oscillations of clock-related genes (BMAL1 and PER2) and transferrin receptor levels in U87 glioma cells, we identified optimal timing for the complexes’ cellular uptake and payload delivery using two complementary computational tools (CircWave and CosinorPy)." (PMID 40649908, 2025). "Our research had elucidated the circadian oscillations of the clock genes in the U87 glioma cells by employing two different computational models and observed that T16 and T8 time points revealed the highest circadian activity for Bmal1 and Per2 genes, respectively." (PMID 40649908, 2025). "Nevertheless, Per2 KD cells also display a significant decrease in wound healing closure as compared to WT cells, strongly indicating that disruption of this clock gene alters the migration, and ultimately the metastatic capacity of these glioma cells." (PMID 38907776, 2024). "Major mutated CRGs in LGG are PER2, BMAL1, CLOCK and BMAL2, which might indicate these genes are most influencial CRGs to glioma development or metastasis." (PMID 39043735, 2024). "In this study, we found that LbGP could inhibit the proliferation of glioma cells and promote the expression of period 2 (PER2) through the PKA-CREB pathway." (PMID 37069338, 2023). "In conclusion, Our results suggest that LbGP can be used as an alternative drug to inhibit glioma proliferation, we speculate that LbGP suppresses the expression of SREBP1c by up-regulating Per2, thus inhibiting lipid synthesis and metabolism in gliomas." (PMID 37069338, 2023). "Taken together, these data show that Per2 mitigates glioma development by downregulating Id3." (PMID 35599595, 2022).
glioma (continued). "Here, we aim to explore whether overexpression of Per2, a tumor suppressor gene, may inhibit the malignant phenotype of glioma based on regulating PTEN/AKT/Smad5/Id3 signaling pathway and would help to identify a novel target for clinical precision medicine." (PMID 35599595, 2022). "Based on these findings, we hypothesized that Per2 is involved in Id3 expression in gliomas, which we explored in subsequent experiments." (PMID 35599595, 2022). "Similarly, PER2 can block the Wnt/β-catenin signaling pathway to limit the stemness of glioma stem cells." (PMID 35606376, 2022). "In glioma cells, the Wnt/β‐catenin signaling pathway was identified as the target of PER2 in GSCs." (PMID 36066207, 2022). "The protein levels of Per2 and Id3 in 59 glioma specimens were assessed using IHC." (PMID 35599595, 2022). "Besides, PER2 possesses potential function in influencing the proliferation and stemness of glioma stem cells in relation to the Wnt/β-catenin signaling pathway to influence." (PMID 35606376, 2022). "Also, through using luciferase reporter genes the core clock gene PER2 exhibited a circadian transcriptional activity in C6 glioma cell lines." (PMID 32195174, 2020). "Moreover, Per2 levels in glioma tissues at ZT8 were lower compared to normal brain tissues at ZT12 (t=-3.218, p<0.01) when cry2 expression was highest in both samples." (PMID 29100427, 2017). "Similarly, lower Per2 levels were observed in glioma tissues at ZT4 compared to ZT24 in normal brain tissues when cry2 expression was lowest in both (t=-2.508, p<0.01)." (PMID 29100427, 2017). "In glioma tissues, the Per2 levels were similar at ZT4 and ZT8 (t=-0.144, p>0.5)." (PMID 29100427, 2017). "Overexpression of Per2 in irradiated glioma induces a decreased of c-Myc mRNA and protein levels." (PMID 28620312, 2017). "In our study, we found that the level of phosphorylated histone H2AX in the gliomas of the Per2-knockdown group after X-ray irradiation was significantly lower than the control virus or normal control groups at all time points, indicating reduced DNA double strand breakage." (PMID 27036047, 2016). "Moreover, when we measured apoptosis in the three glioma groups after irradiation, we found that the apoptosis levels in the Per2-knockdown group were lower, consistent with the changes in DNA damage." (PMID 27036047, 2016). "Additionally, decreased Per1 and Per2 expression increases the efficacy of radiotherapy against glioma by promoting apoptosis." (PMID 27036047, 2016). "Apoptosis in glioma tissue correlated with the level of Per2 expression." (PMID 25760074, 2015). "To determine whether changes in Per1 and Per2 expression may affect the radiation sensitivity of glioma, we measured proliferation and apoptosis of glioma cells when rats were x-irradiated at times when Per1 and Per2 mRNA levels were high and low." (PMID 25760074, 2015). "In addition, the high expression of Per1 and Per2 sensitized the glioma cells to x-irradiation, promoting apoptosis as a result." (PMID 25760074, 2015). "To test whether circadian expression of Per1 and Per2 may be involved in glioma growth, we analyzed expression patterns in both glioma and normal brain tissue." (PMID 25760074, 2015). "This suggests that x-irradiation can increase the expression of Per1 and Per2 in glioma tissue." (PMID 25760074, 2015).
glioma (continued). "Proliferation in glioma tissue correlated with the level of Per2 expression." (PMID 25760074, 2015). "Our results suggest that Per1 and Per2 expression may increase the efficacy of radiotherapy against glioma by promoting apoptosis." (PMID 25760074, 2015). "Overall, our findings suggest that Per2 may be a viable therapeutic target for glioma." (PMID 35599595, 2022). "The results showed that the apoptosis rate of glioma cells was higher when radiotherapy was administered at the peak of Per1 or Per2 expression, indicating that clock genes could act as molecular targets that regulate chronotherapy efficacy and promote personalized therapeutic effects." (PMID 34966277, 2021). "Furthermore, the circadian genes Per1 and Per2 increase the radiosensitivity of gliomas in vivo." (PMID 27036047, 2016). "Another study showed that Per2 expression may increase the efficacy of radiotherapy against glioma." (PMID 27036047, 2016). "Metformin regulates GBM cell lines through the circadian gene PER2 and the SIRT2/G6PD signaling pathway in a PER2-dependent manner, as well as through synergies with the radiotherapy sensitivity of glioma cells." (PMID 40166471, 2025). "As Per2 can target the Wnt/β-catenin signalling cascade in GSCs, the downregulation of important proteins associated with the stemness and invasiveness of GSCs, including c-Myc, MMP9, MMP2, β-catenin, and Wnt7b, might explain the tumor suppressive properties of Per2 in gliomas." (PMID 40495887, 2025). "The differential expression of CCGs in glioma grading confirmed that cluster I genes (ARNRL, NPAS2, and TIMELESS) and CRY1, with cluster II genes (CRY2, DBP, NR1D1, NR1D2, PER2, PER3, and RORA) showed significantly opposite expression trends in brain tissues." (PMID 35832846, 2022). "To this end, we transfected A172 glioma cells with siRNA for PER1 and PER2 before cell synchronization." (PMID 33086741, 2020). "In C6 glioma cells, p38 MAPK inhibition with SB203580 showed to lengthen the period of the Per2::luc reporter." (PMID 32195174, 2020). "In glioma cells and familial breast tumors, Per1 and Per2 expression levels were significantly reduced compared to normal cells or tissues." (PMID 41142939, 2025). "The expression of the Per2 gene was found to be enriched within C6 glioma tumor spheres but not in monolayer cell culture, suggesting that cell interactions or tumor microenvironment (TME) permit circadian timing." (PMID 40495887, 2025). "It was observed that as compared to adjacent non-glioma cells, period CC (Per) genes including Per1 and Per2 were found to be underexpressed in glioma cells." (PMID 40495887, 2025). "For example, glioma, hepatocellular carcinoma, head and neck squamous cell carcinoma, myeloid leukemia, colorectal, pancreatic, gastric, oral, breast, and non-small-cell lung malignancies all have changed expression levels of PER1, PER2, and PER3." (PMID 38892035, 2024). "Such an approach would be especially useful as it was shown for the two clock proteins CRY2 and PER2 that the effects of their expression on radiosensitivity were exclusively observed in glioma, but not in healthy brain tissues." (PMID 38378853, 2024). "Per2 and Id3 maintained separate prognostic abilities and had a negative connection in human glioma." (PMID 35599595, 2022). "Per2 gene expression was enriched within C6 glioma tumor spheres but not in monolayer cell culture, suggesting that cell interactions or TME enable circadian timing." (PMID 36066207, 2022).
glioma (continued). "The same results were achieved in our study with glioma cells in vitro and in vivo models, but we did not examine the particular mechanism by which Per2 reduces malignancies by modifying metabolism." (PMID 35599595, 2022). "The results showed that the Per2 mRNA expression was negatively correlated with the WHO grade, while the Id3 mRNA expression was positively correlated with the WHO grade in patients with glioma in TCGA and CGGA databases." (PMID 35599595, 2022). "Through employing immunohistochemical staining and methylation specific PCR the study revealed that PER2 gene expression is deregulated in 52.17% of the glioma cells relative to the nearby non-cancerous cells which was attributed to promoter methylation." (PMID 32195174, 2020). "All these findings suggest that the PER2 gene exerts a potential role in regulating stemness, self-renewal, cell growth, cell cycle distribution, migration and invasion of GCS in glioma and are consistent with similar results obtained in colon cancer stem-like cells (CCSCs)." (PMID 33114365, 2020). "Circadian genes may potentially influence glioma survival as the overexpression of PER1 and PER2 was found to inhibit the growth and increases apoptosis in tumor cells." (PMID 32195174, 2020). "Similarly, in rat-1 fibroblast and C6 glioma cells, inhibition of p38 MAPK with SB203580 lengthened the period of the PER2::LUC reporter, and inhibition of U2OS cells with SB202190 lengthened the period of a Bmal1-dLuc reporter." (PMID 29316898, 2018). "Many of the core circadian rhythm PAS factors, including the period (PER) genes, are downregulated in breast, colorectal, prostate, glioma and non-small cell lung cancer in humans; moreover, it has been suggested that PER1 and PER2 function as tumor suppressors." (PMID 28177907, 2017). "In glioma tissue, the levels of Per1 and Per2 mRNA were significantly higher in the irradiated group than in the control group when Per1 and Per2 expression was elevated, i.e. at ZT4 for Per1 (t = –4.464, p < 0.001) and ZT0 for Per2 (t = –2.407, p < 0.05)." (PMID 25760074, 2015). "Recent research has demonstrated a strong link between the intensity of CRF and SNPs in the circadian rhythm genes PER2 and ARNTL2 among individuals with glioma, providing valuable insights into how circadian rhythm disruptions may exacerbate fatigue in cancer patients." (PMID 39372868, 2024). "For example, a recent study using a human GSC model showed that PER2 mRNA and protein expressions were downregulated in GSCs compared to non-stem glioma cells, suggesting that PER2 could be involved in the malignant process of glioma." (PMID 36430659, 2022). "Besides, the expression of eight CCGs (CRY2, DBP, NR1D1, NR1D2, PER2, PER3, RORA, and TIMELESS) was negatively regulated by methylation and positively regulated by CNV in glioma, which is consisting with previous studies that DNA methylation and CNV can promote abnormal gene expression." (PMID 35832846, 2022). "Altered expression of PER1, PER2 and/or PER3 have been reported in colorectal, pancreatic, gastric, oral, breast, prostate, bladder, renal, and non-small cell lung cancers, as well as in glioma, hepatocellular carcinoma, head and neck squamous cell carcinoma and myeloid leukemia." (PMID 33114365, 2020). "Although the expression of Per2 changes the growth of glioma, the tumor volume of each group may not differ because of the limited time and limited sensitivity of the gliomas at 24 hours (statistical difference was found in tumor volume at 48 and 72 hours)." (PMID 27036047, 2016). "The authors suggest that since PER2 targets the Wnt/β-catenin signaling pathway in GSCs, the downregulation of critical proteins involved in the invasiveness and stemness of GSCs, such as Wnt7b, β-catenin, MMP2, MMP9, and c-Myc, may explain the tumor suppressive role of PER2 in gliomas." (PMID 34361055, 2021).